STAT3 (signal transducer and activator of transcription 3)
Diseases named in the same sentence as STAT3 in open-access papers (continued):
Sharing a sentence is not in itself a finding about the gene and the disease.
tumor (continued). "In contrast, Xbp1-deficient IECs exhibit increased turnover through NFκB-dependent activation of STAT3, promoting colitis-associated cancer and spontaneous adenomatous polyposis coli (APC)-related tumors in mice, suggesting that XBP1 might act as a tumor suppressor in the intestine." (PMID 28860159, 2017). "As previously discussed, we had developed another small molecule inhibitor of STAT3 (LLL12) that reduced proliferation, and induced apoptosis and cell cycle arrest of a variety of tumor cell lines." (PMID 28750090, 2017). "For example, miR-27a was found to be downregulated and showed tumor-suppressive functions in CRC, targeting Stat3 and Smad2; in other studies, this same miR was found to be upregulated and showed oncogenic functions in CRC." (PMID 28902152, 2017). "We found that SC‐60 treatment showed reduced tumor weight and suppressed tumor growth, increased SHP‐1 activity, and decreased p‐STAT3 and Mcl‐1 expressions in xenografted tumors." (PMID 28084011, 2017). "In summary, we conclude that the ESCC microenvironment promotes tumor angiogenesis by coercing NECs to change toward TECs, with the activation of JAK/STAT3/c-MYC signaling pathway." (PMID 29088816, 2017). "The activation of MDSCs, on the other hand, was induced by heat shock protein 72 on tumor-derived exosomes that triggered TLR2-NFκB signaling, with a subsequent production of IL-6 and activation of STAT3." (PMID 27690299, 2017). "These significative parameters were further subjected to multivariate Cox proportional-hazards model, which demonstrated that the tumor size, TNM stage and STAT3 expression level were correlated strongly with OS and DFS." (PMID 28032598, 2017). "One month after tumor challenge, only one mouse in the PBS group survived, whereas only two mice immunized with STAT3-blocked HCC vaccine established HCC tissue." (PMID 29115974, 2017). "Our findings suggested that OSM suppresses SLUG expression and tumor metastasis of LAC through inducing the inhibitory effect of the STAT1-dependent pathway and suppressing the activating effect of STAT3-dependent signaling." (PMID 27486982, 2016). "STAT3 is a main modulator in inflammation-mediated tumorigenesis, including CRC, by promoting tumor cell proliferation and survival." (PMID 27517746, 2016). "NDRG2 is a relevant biomarker for predicting aggressive behavior, tumor recurrence and overall patient survival, independently or in combination with other factors, such as CD24, phospho-STAT3, and HOXD1." (PMID 26506239, 2016). "Depending on the cell type, the IL-6/STAT3-dependent pathways, such as the JAK/STAT, PI3K/AKT/NF-κB, or p38 MAPK, can enhance tumor growth and refractoriness to chemotherapy." (PMID 26762586, 2016). "By contrast, the strong inhibition of STAT3 phosphorylation induced by NZ decreased the transcription of IDO mRNA, the release of kynurenine in the tumor supernatant and the infiltration of Treg cells." (PMID 26980746, 2016). "In CRPC, the overall expression of phosphorylated S6 was reduced but remained active in certain tumor cells which tended to also express increased phosphorylated ERK and STAT3." (PMID 26910118, 2016). "Tumour cell expression of STAT1 and STAT3 at both cytoplasmic and nuclear locations were combined and identified as STAT1/STAT3 tumour cell expression." (PMID 27769057, 2016). "Here, we demonstrated evidence that EBI3 assist the tumor escape immune surveillance in CRC by mediating a bidirectional reciprocal-regulation STAT3 signaling pathway to induce antitumor CTL response and suppress tumor growth." (PMID 27247488, 2016). "STAT1 and STAT3 have a complex interaction with both tumour cells and the tumour microenvironment including immune infiltrates such that STAT1 and STAT3 are thought to play opposite roles in tumorigenesis, regulating distinct gene signatures." (PMID 27769057, 2016).
tumor (continued). "In fact, examination of the effects of C188-9 on STAT1 in each of our in vitro assays, as well as in tumor xenografts, demonstrated that C188-9 was as effective at targeting STAT1 as it was in targeting STAT3." (PMID 27027445, 2016). "TAMs produced large amounts of both MFGE-8 and IL-6, which coordinately induced tumor potential and CSC chemoresistance through STAT3 and Hedgehog signaling, the latter of which regulates normal stem cell self-renewal." (PMID 26980947, 2016). "In several studies, disruption of STAT3 signaling in tumor cells was shown to drive down TGF-β expression and potentiate NK-mediated killing of tumor targets." (PMID 27148255, 2016). "Based on these concepts, in future studies we propose a series of experiments both to fully elucidate how STAT3 is involved in CPA-7 effects on the immune response and to maximize the tumor inhibition effects of CPA-7 for the clinical treatment of cancer." (PMID 27435207, 2016). "This was accompanied by an increase in the percentage of DNAM-1+ circulating NK cells in the STAT3-targeted mice and enhanced in vitro cytotoxicity toward B16F10 tumor targets." (PMID 27148255, 2016). "Other than PI3K/AKT signaling network, previous reports also demonstrated an essential role of STAT3 and its regulation by PI3K/mTOR signaling in tumor progression." (PMID 27875549, 2016). "Particularly, EBI3 blocking promoted tumor infiltrating Granzyme B+ CTLs and IFN-γ+ CTLs production and restrained CRC cell proliferation through bidirectional reciprocal-regulation STAT3 signaling pathway." (PMID 27247488, 2016). "To investigate the effect of STAT3 and Anxa 2 on tumor metastasis, we observed the migration and invasion of CRC Caco-2 cells, after the manipulation of STAT3 and Anxa 2 by transwell migration/invasion assays." (PMID 27274723, 2016). "The STAT3 pathway is a signaling pathway regulating cell proliferation and apoptosis in CCA cells and has been shown to be an important mediator of tumor resistance." (PMID 26956050, 2016). "In the mouse model, SHH inhibitors significantly reduced tumor incidence and multiplicity, decreased the expression of IL-6, TNF-α, COX-2, STAT3, and NF-κB, and significantly induced apoptosis." (PMID 26716648, 2016). "The transcription factors E2F1, NF-κB, Sp1, HIF-1, AP-1, STAT3, and STAT5 play important roles in tumor cell signal transduction." (PMID 27613831, 2016). "14,15-EET triggered neutrophil infiltration in metastatic lesions byactivating STAT3 and JNK pathways to induce the expression of human IL-8 andmurine CXCL15 in corresponding tumor cells." (PMID 27270316, 2016). "Besides amino acid deprivation, STAT3 phosphorylation in MDSCs has also been linked to the activation of two subunits of NADPH oxidase (NOX2), namely P47phox and gp91phox, leading to an increased generation of intracellular ROS, another mechanism that dampens anti-tumor immunity." (PMID 27029037, 2016). "The impeded cancer progression was due to the inhibitory effect of metformin on STAT3-ERK-vimentin and fibronectin-integrin signaling to decrease tumor cell invasion and de-differentiation." (PMID 27145454, 2016). "Although the molecular mechanisms by which NFIB mediates its anti-tumour effects in GBM remain to be defined, our findings suggest a role for p-STAT3." (PMID 27083054, 2016). "The transcription factors, such as E2F1, NF-κB, Sp1, HIF-1, AP-1, STAT3, and STAT5, play important roles in tumor tube formation." (PMID 27613831, 2016). "Numerous studies have demonstrated constitutive activation of STATs in particular STAT1, STAT3 and STAT5 by cytokines in a large number of diverse human tumor cell lines." (PMID 26993600, 2016). "The median survival of patients showing neither STAT1 nor STAT3 activity (nuclear) in their tumor specimens was at least 33 months shorter in comparison to patients with tumor related activation of STAT1, STAT3 or both proteins." (PMID 27191495, 2016).
tumor (continued). "S100A4 upregulates miR155, which suppresses SOCS1, activates STAT3 signaling and in turn enhances MMP9, promoting tumor invasiveness." (PMID 27029037, 2016). "Our previous finding demonstrated that SSM2 and SSM3 cells display persistent prolactin receptor signaling with activation of JAK2, STAT3 and STAT5A/5B, and that pharmacological inhibition of pJAK2 increased SSM2 and SSM3 tumor cell apoptosis." (PMID 27391074, 2016). "Fanny Chalmin demonstrated that mice tumor-derived exosomal HSP72 induce IL-6 production by MDSCs through activation of TLR2 and its adaptor MyD88, leading to Stat3 phosphorylation and the promotion of MDSC immunosuppressive functions." (PMID 27090786, 2016). "Recently, the alternate complement pathway was found to activate STAT3 in KSHV-infected endothelial cells and KS tumor cells." (PMID 27458446, 2016). "High p-STAT3 levels were confirmed in tumors from three HCC patients (HCC-1, HCC-2, and HCC-3) compared to matched non-tumor liver tissues." (PMID 27259268, 2016). "Interestingly, CX3CR1 and STAT3 have been reported to positively cooperate in modulating the immune interaction between monocytes and smooth muscle cells, indicating this observed signal may be tumor cell-autonomous." (PMID 27855189, 2016). "There are two key STAT subtypes: STAT3, an oncogene which promotes cell survival and proliferation, and STAT1, a tumour suppressor which induces anti-proliferative and pro-apoptotic responses." (PMID 26909593, 2016). "To explore the possible role of EPHA3 in MDR, we assessed the influence of EPHA3 on chemoresistance, cell cycle, apoptosis, and tumor growth, as well as the relationship between EPHA3 and the expression of PI3K, BMX, and STAT3 in SCLC." (PMID 27101199, 2016). "Increased YAP1 and GP130 expression, STAT3 and ERK phosphorylation were also observed in Δhep tumour-bearing livers." (PMID 28000790, 2016). "A research stated that CDK5 was mandatory for the DNA damage response in tumor cells and another study showed that CDK5/STAT-3 oncogenic pathway played a key role in the expression of DNA repair genes." (PMID 27406233, 2016). "This interactions leads to the de-repression of genes downstream of STAT3 and consequentially inhibition of CRC cell proliferation and tumor growth in vitro and in vivo by extending the G0/G1-S phase transition." (PMID 27198161, 2016). "Compared with the STAT3 group or CDDP group, the tumour weight and volume was significantly reduced in the combination group (P<0.05)." (PMID 27129294, 2016). "We identified that there was upregulation of BCL-2/BCL-xL prosurvival signaling and p-STAT3 activation in HCC827 cells in adaptive escape against erlotinib, primarily localizing along the peripheral rind of the tumor xenograft as in the TKI evading cells." (PMID 27852038, 2016). "Also, Stat3 controls cancer cell fate and interaction with the microenvironment; it plays important roles in the maintenance of cancer stem cell populations, switching between epithelial and mesenchymal phenotypes that precede metastasis, and tumor angiogenesis." (PMID 27460364, 2016). "STAT3 and STAT5 phosphorylation clearly plays a pivotal role in the proliferation and survival of a wide variety of tumor cells and that blockade of JAK/STATs signals can provide a potent therapeutic strategy for RCC." (PMID 26911335, 2016). "In NSCLC cell xenograft model, either overexpression of miR-206 or inhibition of 14-3-3ζ inhibited the STAT3/HIF-1α/VEGF pathway and decreased the tumor growth and angiogenesis." (PMID 27806334, 2016). "Moreover, these cells increased in the phosphorylation of PP2A, and subsequent activation of STAT3 at S727 and the expression of Col17a1, suggesting that the suspension survival pathway is a general characteristic in enriched TICs derived from a variety of tumours." (PMID 27306323, 2016). "Taken together, these data demonstrated that knocking down DR6 suppressed tumor angiogenesis through NF-κB, IL-6/P38 MAPK and IL-6/STAT3 signaling." (PMID 26950598, 2016).
tumor (continued). "Similar to the orthotopic location, we now find that SSM2 tumor cells growing in bones of OVX mice show phosphorylation of JAK2 and STAT3, suggesting activation of the PrlR signaling pathway in the absence of estrogen." (PMID 27391074, 2016). "Reported evidence indicated that overexpression of miR-26a can either reduce STAT3 phosphorylation in colon mucosa or suppress tumor growth and metastasis through IL6-STAT3 signaling." (PMID 27683108, 2016). "Legumain targeted nanoparticles encapsulating hydrazinocurcumin suppressed STAT3 and re-educated TAMs, to be IL-12high, IL-10low and TGF-βlow, which resulted in suppression of tumor growth, metastasis and angiogenesis in vivo." (PMID 27886105, 2016). "Combining blockade of p-STAT3 with cytotoxic drugs cisplatin, docetaxel, 5-fluorouracil (TPF) enhanced the antitumor effect in vitro and in vivo with decreased tumor sphere formation and SP cells." (PMID 26556875, 2015). "In line with the alterations of tumor microenvironment contributing to PCSLC expansion under ADT, a large set of evidence reveals a critical role of the IL-6/JAK/STAT3 pathway in PCSLC enrichment under ADT." (PMID 26593949, 2015). "The roles of JAK/STAT3 in NED- and CR-related processes, most notably tumor growth, are still debated." (PMID 25785244, 2015). "STAT3 acetylation, another activation form of STAT3, can also contribute to regulate DNMT1 binding to several tumor-suppressor gene promoters and promote the promoter methylation of relative genes and the development of cancer." (PMID 26631279, 2015). "Given that the downstream intracellular targets of CXCL8 include STAT3, increased CXCL8 in the tumour stroma promotes a positive intercellular feedback loop between CXCL8 and IGF-2 production." (PMID 26465273, 2015). "Recently, the relationship between STAT3 and BCL3 has been demonstrated in carcinoma and tumor survival." (PMID 26219963, 2015). "Tumor-derived cytokines, such as GM-CSF, M-CSF, G-CSF, IL-6 and VEGF, initiate the first kind of signaling pathways that converge on activation of STAT3 and STAT5." (PMID 26285119, 2015). "Based on in vitro studies and xenograft models, STAT3 is considered to play a tumour-promoting role in EGFR mutant NSCLC13, 14, 16, 18, therefore, inhibition of STAT3 is considered as therapeutic intervention in lung ACs46." (PMID 25734337, 2015). "In summary, our results suggest that STAT3 represses NF-κB-dependent CXCL1 expression by sequestering NF-κB in the cytoplasm and mechanistically delineate a novel tumour-suppressive pathway governed by the STAT3–NF-κB–CXCL1 axis." (PMID 25734337, 2015). "Another possibility is that STAT3 activation is an early step in feline OSCC carcinogenesis and reliance on STAT3 signaling pathways is lost in later stages of tumor development." (PMID 26272737, 2015). "Intraperitoneal injections of JSI-124 resulted in pronounced decrease in tumor cell proliferation and CD34-positive endothelial cells, and marked reduction expression of p-VEGFR2 and p-STAT3 in solid tumors." (PMID 25789853, 2015). "In the case of the mutant PDGFRα proteins, we observe a strong and long lasting activation of STAT1, STAT3 and STAT5, which will undoubtedly have a much more prominent effect on the cells and/or the tumour microenvironment." (PMID 25880691, 2015). "Nevertheless, although late-stage Stat3-deficient tumours failed to respond to an anti-CXCL1 monotherapy, the use of CXCL1 blockers combined with standard chemotherapy or as maintenance therapy could be a reasonable alternative to treat these tumours and it deserves further investigation." (PMID 25734337, 2015). "Recent study has indicated that constitutive STAT3 signaling induces vascular endothelial growth factor (VEGF) expression and tumor angiogenesis." (PMID 26464811, 2015). "In vitro inhibition of STAT3 activity with either JAK inhibitors or STAT3 knockdown results in decreased cell proliferation and increased apoptosis in ABC tumor cell lines." (PMID 26575169, 2015).
tumor (continued). "It's well-known that activation of STAT3 culminates in the transcription of its target genes and that EGF signaling relevant to tumor growth and metastasis is partially mediated by JAK1/2 phosphorylation." (PMID 25915156, 2015). "STAT3 knockdown showed a reduction in BMIC self-renewal and migration, and decreased tumor size in vivo." (PMID 26314961, 2015). "Blocking of Stat3 by WP1066 resulted in reduced VEGFR-induced signaling and angiogenesis, which further supports the role of Stat3 in the interaction of tumor cells and endothelial cells." (PMID 25881542, 2015). "Mitochondrial STAT3 is involved in maintaining optimal oxidative phosphorylation levels in cardiac and nerve cells as well as in RAS-transformed tumor cells." (PMID 26106584, 2015). "After analysis with the Millipore MultiplexMAP bead assay, whole cell lysates of SUM149 cells showed increased Stat3 and NF-κB phosphorylation following incubation with TCR-CM, suggesting that this CM is capable of inducing these pathways in tumor cells." (PMID 26207636, 2015). "Many tumor-produced factors, such as IL-10, IL-6 and VEGF, activate STAT3 by efficient feed-forward mechanisms." (PMID 26512963, 2015). "Icaritin administration potently inhibited the growth of the tumor formed by PLC/PRF/5 cells in NOD/SCID mice, which was accompanied by a reduction of p-Stat3 (Y705) level." (PMID 26376676, 2015). "Evidence suggests that IL-8 modulates tumour angiogenesis by up-regulating the expression of the HIF-1, NF-κB, and STAT3 transcription factors." (PMID 26593962, 2015). "Tumour angiogenesis is modulated by IL-8 via the up-regulated expression of the HIF-1, NF-κB, and STAT3 transcription factors." (PMID 26593962, 2015). "The list of STAT3 target genes includes VEGF, Bcl2, c-myc, cyclin D1, Survivin and WASF3, a member of the WASP/WASF family, which are involved in tumor development and progression." (PMID 28031890, 2015). "A previous study confirmed that JAK/STAT3 and PI3K/Akt pathways were involved in inhibiting the proliferative and angiogenic potential of tumor cells." (PMID 25695729, 2015). "ELISA analysis revealed increased expression of STAT3-activating cytokines such as EGF, OSM and IL-6 in lungs harbouring KrasG12D-driven tumours compared with healthy control lungs." (PMID 25734337, 2015). "Taken together, STAT3 played an important role for precancerous progression to invasive ones, metformin could efficiently inactivate STAT3, and as a result, transcription of its target genes was inhibited, leading to suppression of tumor development or tumorigenesis." (PMID 26245871, 2015). "We euthanized the tumor-bearing mice, collected the tumors, extracted the proteins and found that HHT downregulated the STAT3 phosphorylation." (PMID 26166037, 2015). "Targeting of the STAT3 protein was shown to effectively kill GBM cells and suppress GBM tumor growth." (PMID 25638155, 2015). "In numerous inflammatory cells and tumor cells, IL-17 mediates signaling through distinct pathways, such as the MAPK, NF-κB, and STAT3 pathways." (PMID 26524953, 2015). "Both Stat3 and HIF-1α have been revealed to drive tumor angiogenesis, metastasis and drug resistance." (PMID 26202747, 2015). "In hypoxic tumor microenvironments, several signals can trigger VEGF-A expression and secretion, including among others STAT3." (PMID 26317647, 2015). "It has been reported that constitutive activity of STAT3 up-regulated VEGF expression and tumor angiogenesis." (PMID 25865044, 2015). "To explore the mechanism underlying the functional interplay of NOX4 and IL-6 in enhancing A549 tumor growth and survival of NSCLC cells in vivo, we sought to determine the reciprocal activation between NOX4/Akt and IL-6/STAT3 signalings in vivo." (PMID 25504436, 2015). "IL–20 induced the expression of N-cadherin, STAT3, vimentin, fibronectin, RANKL, cathepsin G, and cathepsin K, all of which are involved in cancer cell migration, EMT, and tumor-induced osteolysis." (PMID 26440411, 2015).